BRCA2 (BRCA2 DNA repair associated)
Diseases named in the same sentence as BRCA2 in open-access papers (continued):
Sharing a sentence is not in itself a finding about the gene and the disease.
uterine cancer (9 papers, 2017 to 2024). Primary or metastatic malignant neoplasm involving the uterine corpus and/or the cervix. "We found that PD-L1 in tumours (breast, stomach, colorectal and uterine cancers) with BRCA2, PALB2 or Ku70/80 mutations showed higher expression than in tumours without such mutations." (PMID 29170499, 2017). "BRCA1 or BRCA2 mutation can marginally increase cervical and uterine cancer incidence." (PMID 34577828, 2021). "Compared to the general population, women with a deleterious BRCA1 or BRCA2 mutation had a roughly 2.5-fold greater risk of getting uterine cancer, according to the cohort study on the rate of BRCA mutation in uterine cancer." (PMID 38297203, 2024). "One of the studies just reported the prevalence of BRCA1 in uterine cancer cases and one of them didn’t segregate the BRCA1 and BRCA2 prevalence." (PMID 38297203, 2024). "Second, the reason that the results for uterine cancer were lower than those of other cancers is that BRCA1 and BRCA2 mutant genes are related to both breast and uterine cancer." (PMID 36142316, 2022).
childhood cancer (8 papers, 2012 to 2024). "Bi-allelic BRCA1 mutations are likely to be lethal at the embryonic stage, while such mutations in BRCA2 lead to Fanconi anemia type D1, with increased risk of childhood cancer." (PMID 35356428, 2022). "Initial studies investigating a potential role of germline BRCA1 and BRCA2 PGVs also for predisposition for non-syndromic childhood cancer focussed on the incidence of childhood cancers in the offspring of families presenting with HBOC, in which a germline BRCA1/2 PGV had been detected." (PMID 34680915, 2021). "Two large scale studies identified germline BRCA2 PGVs in a small number (13/2081 total across both studies) of childhood cancers and just one germline BRCA1 PGV." (PMID 34680915, 2021). "Here we review aspects of the clinical, genetic, and biological role of BRCA1 and BRCA2 in the context of FA and childhood cancer and discuss clinical and biological implications." (PMID 34680915, 2021). "In the St Jude’s cohort of long-term survivors of childhood cancer germline BRCA1/2 PGVs were detected in 34 (BRCA2 n = 20, BRCA1 n = 14)/4402 individuals." (PMID 34680915, 2021). "In turn, recent large genetic studies of individuals affected by apparently sporadic childhood cancer detected BRCA1/2 variants, which point also towards a possible role for germline PGVs in particular of BRCA2 in the development of some non-syndromic childhood cancers." (PMID 34680915, 2021).
embryonal tumors (8 papers, 2019 to 2025). "Subtle dysfunction could be biologically relevant and very important given the high rate of embryonic cancers in BRCA2-associated FA." (PMID 40724944, 2025). "Classically, these patients present with congenital abnormalities and are predisposed to leukemia and embryonal tumors at an early age, although the presence of certain BRCA2 variants may result in milder disease (1, –3)." (PMID 40854122, 2025). "In patients with FANCD1/BRCA2 or FANCN/PALB2 variants, additional screenings for embryonal tumors (e.g., brain MRI, abdominal ultrasound, and urine catecholamine) are recommended." (PMID 40970532, 2025). "Patients with biallelic PVs in FANCD1/BRCA2 and FANCN/PALB2 have very high risks of malignancies, and they can develop embryonal tumors which are not seen in patients with FA who have PVs in other FANC genes." (PMID 36091172, 2022).
familial hypercholesterolemia (8 papers, 2012 to 2025). An inheritable form of hyperlipidemia, in which there are excess lipids in the blood. "It has been suggested for several diseases that extreme PGS risk confers a similar magnitude of increased risk as the presence of Mendelian pathogenic variants (for example, familial hypercholesterolemia for coronary artery disease, and BRCA1 or BRCA2 for breast cancer)." (PMID 39966645, 2025). "Combining a microfluidic amplification system with massive parallel sequencing is an effective method for mutation scanning, which has previously been employed for the diagnostics of familial hypercholesterolemia and here was applied to BRCA1 and BRCA2 sequencing." (PMID 23110154, 2012).
hepatocellular carcinoma (8 papers, 2017 to 2026). A malignant tumor that arises from hepatocytes. "Extending these observations to tumor cell growth, we found that shRNA-mediated BRCA2 knockdown causes a significant reduction in the clonogenic survival of HuH1 hepatoma cells." (PMID 28743957, 2017). "Regarding hepatocellular carcinoma (HCC), evidence about its link with BRCA1 and BRCA2 mutations is extremely limited." (PMID 33198203, 2020). "BRCA2 overexpression was able to partially restore colony formation in USP21-depleted hepatoma cells, supporting a role for BRCA2 as a mediator of USP21-dependent tumor growth." (PMID 28743957, 2017). "Consistent with our previous findings, USP21 knockdown in hepatoma cell lines resulted in reduced BRCA2 expression and a concomitant increase in DNA damage, as measured by H2AX phosphorylation." (PMID 28743957, 2017). "Moreover, we show that USP21 is overexpressed in hepatocellular carcinoma, where it promotes BRCA2 stability and inversely correlates with patient survival." (PMID 28743957, 2017). "Importantly, we find that USP21 is the most highly amplified DUB in hepatocellular carcinoma (HCC), a BRCA2-proficient tumor with poorly understood molecular pathways of carcinogenesis, a scarcity of druggable targets and a dismal therapeutic outcome." (PMID 28743957, 2017). "Using a model of chemically induced hepatocellular carcinoma in mouse liver, we comparatively analyzed the dynamics of transcript levels for several genes (BRCA1, BRCA2, CHEK1, CHEK2, ATM, CDK12) in paired samples of normal and tumor tissue over a 24-h PMI using RT-qPCR." (PMID 42073491, 2026).
neurofibromatosis type 1 (8 papers, 2019 to 2025). A clinically heterogeneous, neurocutaneous genetic disorder characterized by cafe-au-lait spots, iris Lisch nodules, axillary and inguinal freckling, and multiple neurofibromas. "Interestingly cells from cancer syndromes show either a maximal number of MRE11 foci from 10 min to 1 h after 2 Gy X-rays (e.g., retinoblastoma, tuberous sclerosis complex, and neurofibromatosis type 1) or the MRE11 foci are impaired (e.g., in BRCA1-, BRCA2-, BLM-, FANC-, and ATM-mutated cells)." (PMID 37626928, 2023).
uveal melanoma (8 papers, 2014 to 2026). A melanoma derived from melanocytes of the uveal tract. "Only one study related to BRCA2 focused on uveal melanoma with increased incidence." (PMID 34577828, 2021).
head and neck squamous cell carcinoma (7 papers, 2018 to 2024). A squamous cell carcinoma that arises from any of the following anatomic sites: lip and oral cavity, nasal cavity, paranasal sinuses, pharynx, larynx, and salivary glands. "Moreover, overexpression of SET fails to induce up-regulation of ATM, BRCA1 and CHK2 and recruitment of BRCA2 to DNA damage foci in head and neck squamous cell carcinoma (HNSCC) lines upon cisplatin treatment, suggesting another important inhibitory role of SET on DNA damage repair." (PMID 36345878, 2022).
metastatic carcinoma (7 papers, 2017 to 2025). A carcinoma which has spread from the original site of growth to another anatomic site. "Enrolling patients with tumors harboring pathogenic mutation genes other than ATM, BRCA1 and BRCA2 was challenging owing to the low prevalence of pathogenic alterations affecting these genes in patients with metastatic cancer (<1%)." (PMID 37277454, 2023). "Finally, there seemed more metastatic carcinomas carried BRCA2 mutation as compared to the primary tumors, which suggests an increasing role of PARP inhibitors in the treatment of metastatic pancreatic cancer." (PMID 39941707, 2025). "There is uncertainty about the association between CRC and BRCA2 mutations and also, even though most cancers metastasize to the liver, acute liver failure (ALF) from metastatic cancer and specifically CRC is uncommon." (PMID 39156267, 2024). "Secondly, genetic characteristics of BRCA2 wild-type localized cancer may be different from those of BRCA2 wild-type metastatic cancer." (PMID 36362213, 2022). "We identify inactivation of BRCA1, BRCA2, RAD51C, and PALB2 as the most frequent genetic cause of HRD pan-cancer in both primary and metastatic cancer, with the latter two genes resulting in the same mutational footprints as BRCA2 (consistent with the findings of recent studies in breast cancer)." (PMID 33149131, 2020).
rectal cancer (7 papers, 2018 to 2025). A primary or metastatic malignant neoplasm that affects the rectum. "In this study, we describe a case of an index patient with FAP and rectal cancer harboring germline mutations in both APC and BRCA2, as well as somatic ERBB2 mutations." (PMID 39985003, 2025). "In conclusion, we present a rare case of a de novo FAP patient with rectal cancer, characterized by double germline mutations in APC and BRCA2, alongside somatic ERBB2 mutations." (PMID 39985003, 2025). "Besides, Some of the included studies did not distinguish between BRCA1 and BRCA2, and some did not distinguish between colon and rectal cancer." (PMID 37644384, 2023).
retinoblastoma (7 papers, 2018 to 2023). A malignant tumor that originates in the nuclear layer of the retina. "In addition, the use of WBC sequencing revealed the germline origin of observed copy number deletions in ATM, BRCA2, and for two patients with retinoblastoma, RB1, based on deletions in their matched WBC sample." (PMID 34145282, 2021).
astrocytoma (6 papers, 2004 to 2026). "Wildtype BRCA2 compared with mutated BRCA2 (HR, 0.42; 95% CI, 0.20-0.90; p = .024) and Central Nervous System World Health Organization (CNS WHO) grade 2 astrocytoma compared with grade 3 disease (HR, 0.40; 95% CI, 0.21-0.78; p = .007) were associated with better OS." (PMID 40575414, 2025).
ataxia telangiectasia (6 papers, 2013 to 2025). Ataxia-telangiectasia is the association of severe combined immunodeficiency (affecting mainly the humoral immune response) with progressive cerebellar ataxia. "Seven of these patients were found to carry two pathogenic variants including one biallelic ATM carrier with a clinical diagnosis of ataxia-telangiectasia, two ATM/BRCA2 carriers, one BRIP1/BRCA2 carrier, one BRCA1/CHEK2 carrier, one BARD1/PALB2 carrier, and one CHEK2/PALB2 carrier." (PMID 28008555, 2017).
biliary tract cancer (6 papers, 2021 to 2024). "Overall occurrence of BRCA mutations in biliary tract cancers has been reported as 3.6% with a BRCA2 predominance (0.6% have a BRCA1 mutation and 3% have a BRCA2 mutation)." (PMID 38903278, 2024). "Moreover, according to a meta-analysis, BRCA2 mutation carriers had an increased risk for gastric, esophageal, and biliary tract cancers but not significantly with any other GI cancers." (PMID 37113971, 2023). "Consequently, 315 pathogenic BRCA variants were identified, and an odds ratio of greater than 4.0 were found for biliary tract cancer in BRCA1, esophageal cancer in BRCA2, and gastric cancer in BRCA1 and BRCA23." (PMID 37113971, 2023).
breast adenocarcinoma (6 papers, 2013 to 2025). "Such dedifferentiation with small-cell recurrence has similarly been described in breast adenocarcinoma in a germline BRCA2 mutation carrier." (PMID 28487881, 2017). "HBOC is due to mutations in the BRCA1 and BRCA2 genes and is characterized by breast adenocarcinoma and/or epithelial ovarian carcinoma." (PMID 24625245, 2014). "HBOC is due to mutations in the BRCA1 and BRCA2 genes; it is characterized by ductal or lobular breast adenocarcinoma and epithelial ovarian carcinoma." (PMID 24625245, 2014). "Moreover, a significantly elevated frequency of several BRCA2 polymorphisms—including rs55886062, rs3918290, rs12721655, rs4987117, rs2229774, rs11203289, rs137852576, rs11571833, rs80359062, and rs11571746—was observed in patients with breast adenocarcinoma compared to healthy controls." (PMID 40843725, 2025). "Thus, we present this unusual case of a BRCA2 carrier who presented seven years after her initial diagnosis of breast adenocarcinoma with a new lump in the left axillary tail, which proved to be small cell carcinoma." (PMID 25671134, 2015).
carcinoma in situ (6 papers, 2008 to 2020). "VUS BRCA2 variants were observed with significant differences in patients with invasive tumor with respect to patients with in situ carcinoma (70% vs. 30% respectively, p = 0,014 Fisher Exact test)." (PMID 32806537, 2020). "In women with a germline mutation in BRCA1 or BRCA2, occult malignancy of serous histology, intraepithelial carcinoma or dysplasia is frequently found in the fimbrial end of the FT at the time of prophylactic surgery." (PMID 18612378, 2008).
clear cell carcinoma (6 papers, 2016 to 2023). "The results showed germline positive in 14 patients, 8 BRCA 1 mutation and 6 BRCA2 mutation; 13 of which were high grade serous cancer and only 1 was clear cell carcinoma." (PMID 32856869, 2020). "However, 2 out of 3 patients with clear cell carcinoma had somatic BRCA2 mutation (87.7%) and only 1 patient (33.3%) had germline BRCA2 mutation." (PMID 32856869, 2020). "However, BRCA2 mutation was found only in clear cell carcinoma." (PMID 32856869, 2020). "Conversely, only a small fraction of clear cell carcinomas harbored BRCA1 or 2 mutations (8% for both BRCA1 and BRCA2)." (PMID 31771620, 2019).
depression (6 papers, 2000 to 2023). "The intent of this study was to evaluate the effect that an awareness of being a BRCA1 or BRCA2 mutation carrier has on the attitude towards prophylactic surgery and on developing depression symptoms." (PMID 10755396, 2000).
hereditary tumor syndromes (6 papers, 2019 to 2026). "In this study, in addition to two novel SNVs, BRCA1 p.Y809H (3/49) and BRCA2 p.Y57*(1/49), a known pathologic SNV of BRCA2 (c.3396delA, p.K1132Nfs) (Hereditary cancer-predisposing syndrome) was also identified in 44.91% (22/49) of GIST tumors." (PMID 34805171, 2021).
invasive lobular carcinoma (6 papers, 2016 to 2025). "The results revealed that there were significantly fewer invasive lobular carcinomas among male BRCA2 mutation carriers than among female BRCA2 mutation carriers [odds ratio (OR) 0.14, 95 % confidence interval (CI) 0.05–0.43]." (PMID 26857456, 2016). "Among the 10 patients with invasive lobular carcinomas, BRCA2 positivity was detected in only 1 patient." (PMID 30713775, 2019). "Patients with AKT pathway mutations were older (p = 0.002) and had a higher rate of invasive lobular carcinoma (ILC) histology (p = 0.001), progesterone receptor (PgR) positivity (p = 0.006), and bone metastases (p = 0.001), and a lower rate of germline BRCA2 (p < 0.001)." (PMID 39466567, 2025).
lobular carcinomas (6 papers, 2009 to 2024). "We also found significantly fewer lobular carcinomas among male than female BRCA2 mutation carriers." (PMID 26857456, 2016). "One patient with lobular carcinoma had two CDH1 mutations and one ERBB2 mutation at ~16% allelic fraction, as well as a distinct set of mutations in PTEN, BRCA2 and PMS2 at ~5% allelic fraction." (PMID 24326041, 2013). "Although reports suggesting lobular carcinomas are more frequent in BRCA2 carriers, no similarly defined phenotype has been described for BRCA2-associated tumours, which usually show a ductal, no special type morphology and ER positivity." (PMID 19724277, 2009). "Although reports suggest that lobular carcinomas may be more frequent in BRCA2 carriers, no specific molecular phenotype has been described for BRCA2-associated tumors, which usually show a ductal, no-special-type morphology and ER positivity." (PMID 22537934, 2012).
lung squamous cell carcinoma (6 papers, 2015 to 2023). "In samples of African ancestry, we identified two associations, BRCA2 in lung squamous cell carcinoma (LUSC) and ovarian serous cystadenocarcinoma (OV)." (PMID 32471518, 2020). "Somatic mutations of BRCA1 and BRCA2 were significantly associated with HRD in BRCA, OV, and BLCA, and lung squamous cell carcinoma (LUSC) (FDR < 0.002)." (PMID 34572800, 2021).
ovarian serous cystadenocarcinoma (6 papers, 2017 to 2023). A malignant serous cystic epithelial neoplasm arising from the ovary. "To establish the clinical relevance of our results, we investigated the immune response gene expression in BRCA2-deficient ovarian serous cystadenocarcinomas using mRNA expression data available in The Cancer Genome Atlas (TCGA)." (PMID 31316060, 2019).
adenoma (5 papers, 2014 to 2023). A neoplasm arising from the epithelium. "In this study, the results of qPCR indicated that the highest levels of BRCA1 are presented in a complex carcinoma (CCa1), while cultured cells obtained from a complex adenoma showed the highest levels of BRCA2, followed by complex carcinomas." (PMID 28945747, 2017). "In adenoma vs. normal samples, BRCA2/1 and RAD51 expression was reduced." (PMID 24641873, 2014). "In particular, higher methylation levels of CDKN2B, RASSF1, CHFR, BRCA2 and IGSF4 were observed in adenomas that recurred." (PMID 25091577, 2014).
bone cancer (5 papers, 2019 to 2022). A primary or metastatic malignant neoplasm affecting the bone or articular cartilage. "However, BRCA1 and BRCA2 mutations can increase bone cancer incidence based on one and two studies, respectively." (PMID 34577828, 2021). "Although the bone tumors associated with mutations in BRCA2 have been seldom studied, and the possible function of BRCA2 is far less certain, we think the germ-cell mutation of BRCA2 may be the main reason of occurrence of quadruple neoplasms for this case." (PMID 32571290, 2020).
endometrioid carcinoma (5 papers, 2015 to 2023). "Tier IA variants were found in BRCA1 and BRCA2 genes from three ovarian high grade serous carcinomas and one uterine endometrioid adenocarcinoma, respectively." (PMID 36010253, 2022). "Two patients with OC (HGSC and endometrioid carcinoma, respectively) carried both BRCA1 and BRCA2 mutations simultaneously." (PMID 37064128, 2023). "We excluded from our analyses, low-grade endometrioid adenocarcinomas, mucinous cancers and mixed cell carcinomas lacking serous components, as these are least likely to harbour germline BRCA1/BRCA2 mutations." (PMID 25884701, 2015).
familial prostate cancer (5 papers, 2009 to 2025). Prostate carcinoma that has developed in relatives of patients with a history of prostate carcinoma. "Hereditary prostate cancers, also associated with BRCA2 mutations, have been suggested to have an accelerated tumor development an aggressive phenotype." (PMID 27013479, 2016).